AHR (aryl hydrocarbon receptor)
Diseases named in the same sentence as AHR in open-access papers (continued):
Sharing a sentence is not in itself a finding about the gene and the disease.
tumor (continued). "Moreover, high levels of AhR were found with recurrent/persistent diseases (p = 0.031), particularly when tumours showed a concomitant high N-cadherin expression (p = 0.043)." (PMID 34640369, 2021). "At the same time, rutaecarpine can also regulate other migration and tumor-related gene expression which might be potentially regulated by AhR." (PMID 34955744, 2021). "Notably, Liu and her colleagues reported that Kyn derived from tumor repopulating cells mediated the activation of AhR in T cells to suppress the inflammatory response in the tumor microenvironment." (PMID 34657635, 2021). "Thus, in a tumor-promotion experiment mice with a constitutively activated AhR developed more liver tumors than wild-type mice." (PMID 34595563, 2021). "Overall, these pieces of evidence make AhR-expressing immune cells attractive cellular targets, whereby AhR interference would represent an important means of tipping the immune balance in favor of immunity, as it would desirable in tumor immunotherapy." (PMID 33924971, 2021). "This suggest that the level of AhR expression and the modulation of its activity by specific ligands may drive oncogenesis or suppress tumor development." (PMID 33451095, 2021). "Indeed, it appears that the consequences on tumor progression are completely different depending on the tumor type, the function of the ligand (AhR agonist or antagonist), and the cellular and protein context." (PMID 33451095, 2021). "Previous studies have demonstrated that Kyn could activate the AhR signaling pathway to modulate tumor progression." (PMID 34657635, 2021). "An IL4I1-driven AhR activity though KYNA increases tumour cell motility and T-cell proliferation." (PMID 34680327, 2021). "Whereas the role of AHR in establishing an immunosuppressive tumor niche is well recognized, it remains unclear, whether AHR activation in hepatic progenitor cells might impact on liver carcinogenesis." (PMID 34075438, 2021). "Aryl hydrocarbon receptor (AHR) plays an important role in tumor development." (PMID 34784845, 2021). "In this model, liver tumor formation and growth were significantly higher than in control mice, with AhR−/− hepatocytes showing significantly higher numbers of 4N cells, increased expression of proliferative markers, and the repression of tumor suppressor genes." (PMID 33451095, 2021). "Additionally, administration of microbial indolic metabolites, diindolylmethane or I3C (AhR ligands), reduces tumor formation in ApcMin/+AhR+/+ and ApcMin/+AhR+/- mice indicating that specific microbial indoles are protective against carcinogenesis." (PMID 33916690, 2021). "In contrast to our hypothesis that anthropometric factors would influence tumor levels of AhR and aromatase, only a marginal association between WHR and AhR was found." (PMID 34094928, 2021). "Interestingly, AHR and HIF-1α share the dimerization partner ARNT/HIF1β, showing linked processes of tumor progression, metabolic pathways, and vascular development." (PMID 34572746, 2021). "Targeting AhR must be patient- and tumor-specific and dependent on AhR expression and activation." (PMID 33451095, 2021). "Furthermore, previous data suggest that AhR affects tumor development, as well as immune responses within the tumor environment via tumor-associated macrophages." (PMID 34290693, 2021). "Interrupt of AhR signals by PDM2 revealed improved outcomes in subcutaneous tumor-bearing mice." (PMID 34657635, 2021). "To date, it is still not clear whether AhR ligands located in the tumor microenvironment can modulate AhR activity to the point that it influences tumor development." (PMID 33451095, 2021). "Interestingly, due to the activation of AHR, tumor cells express high levels of IDO1 and TDO2 to promote plasticity." (PMID 33692337, 2021). "Likewise, AHR critically influences NK cell function; upon ligand-dependent activation, AHR promotes anti-tumor cytotoxicity as well as INFγ production." (PMID 34075438, 2021).
tumor (continued). "Kynurenine, a metabolite of tryptophan, upregulates T-cell PD-1 levels by inducing and activating the aryl hydrocarbon receptor (AhR), while AhR upregulates transporters to promote T cells to uptake kynurenine, forming a positive feedback loop and inhibiting anti-tumor immune responses." (PMID 33511116, 2020). "This germline exon 10 AHR variant (GRCh37/hg19, Chr7:g.17379197C > T; ENST00000242057; c.1748C > T/p.Thr583Met) was present in the heterozygous state in both germline DNA (30/65 reads) and tumour DNA (86/177 reads)." (PMID 31996203, 2020). "The role of AhR in carcinogenesis has been a subject of debate, given that this protein may act as either an oncogenic protein or a tumor suppressor in different cell types and contexts." (PMID 32325928, 2020). "The antioxidant, immune-regulatory, mitochondria-optimising and cancer apoptosis-inducing effects of melatonin, coupled to NAS trophic effects, make AhR regulation of the melatonergic pathway an important aspect of tumours and the tumour microenvironment as well as chemoresistance." (PMID 33375613, 2020). "The role of the AHR within the tumor microenvironment has been recently reviewed." (PMID 33348604, 2020). "Cancer immunotherapies can yield poor results, and one of the reasons is that activation of AhR by kynurenine leads to the formation of immunotolerant dendritic and regulatory T cells, which contribute to the creation of an immunosuppressive tumor microenvironment." (PMID 32325928, 2020). "Carbidopa treatment increases AHR protein level and decreases AR protein level in tumor tissues." (PMID 32404918, 2020). "However, the mechanisms for AhR-induced hepatotoxicity and tumor propagation in the liver remain to be revealed, due to the wide variety of AhR ligands." (PMID 32183141, 2020). "Therefore, we next investigated the extent of altered tumor immunity in the context of Kyn-AHR pathway activation to further delineate the mechanisms underlying IDO-induced immune suppression using the B16IDO model." (PMID 32782249, 2020). "B[a]P is a tumor initiator that binds and forms a complex with the aryl hydrocarbon receptor (AhR)." (PMID 32670863, 2020). "To investigate a potential LOH we performed direct sequencing analysis of the genetic locus of AHR in tumor DNA of patients carrying or not this germline variant." (PMID 33281746, 2020). "This suggests that inhibition of Trp breakdown or KYNs/AhR signaling might be a promising therapeutic target in cancer to modulate the immunosuppressive tumor microenvironment." (PMID 32957545, 2020). "The AHR-pathway also plays an important tumor suppressive role in lung inflammation." (PMID 32963246, 2020). "In addition, kynurenine generated by the IDO1 pathway, binding and activating the aryl hydrocarbon receptor (AhR), promotes Treg differentiation and immune suppression and fosters tumor cell survival and motility." (PMID 33986723, 2020). "Additionally, AHR leads to production of adenosine within the tumor microenvironment, ultimately leading to the blunting of T-cell, NK cell and macrophage function." (PMID 33138184, 2020). "In addition to its role in detoxification of these chemicals, AHR has also been shown to promote tumour formation and progression and teratogenesis." (PMID 33260776, 2020). "However, it has been revealed that AhR has both pro-oncogenic and suppressor-like functions depending on the type of tumor." (PMID 32899152, 2020). "IDO may inhibit intratumoral T-cell activity through the depletion of tryptophan in the tumor microenvironment or by recruiting immunosuppressive cells such as MDSCs and Tregs through activation of the aryl hydrocarbon receptor (AhR) by kynurenine." (PMID 33008010, 2020). "Moreover, genomic and functional studies demonstrated that the AhR exhibited tumor suppressor-like activity and inhibited GBM invasion." (PMID 32731514, 2020).
tumor (continued). "Finally, a thorough study of the signaling pathway responsible for this effect underlined the IDO/Kyn/AhR cascade and serine-phosphorylation of STAT3 as the effectors, providing new insights into tumor dormancy mechanisms associated with IFNs." (PMID 32296435, 2020). "The interactions of O-GlcNAcylated TET with the AhR/AHRR and mitochondrial function in cells of the tumour microenvironment will be important to determine, especially as this has been proposed to underpin AhR-driven active DNA demethylation and thereby epigenetic memory." (PMID 33375613, 2020). "It was hypothesized that this apparently mutually exclusive function of AhR in tumour progression may be partially dependent on the specific role of various cell types in the process of migration." (PMID 31659416, 2020). "The differential tumour suppressor and proto-oncogenic effects of AHR are yet to be fully elucidated but may depend on cell type." (PMID 31996203, 2020). "For example, several laboratories are now identifying how the AHR, the gut microbiota, and the tryptophan metabolites they produce can be targeted to influence not only metabolic disease states, but neoplastic diseases as well." (PMID 33374508, 2020). "These new results add support to the hypothesis that increased AHR activity plays an important role in tumor aggression." (PMID 33396563, 2020). "AHR is expressed in multiple tumor types, cancer cell lines, and tumors from animal models." (PMID 32404918, 2020). "This would suggest that the suppressed/exhausted response of the endogenous anti-virals in SARS-CoV-2 infection may be mediated by increased AhR activation, paralleling their immune-suppression in the tumour microenvironment." (PMID 32867244, 2020). "As well as intracrine kynurenine effects, cancer cells also release kynurenine, which activates the AhR on tumour microenvironment cells, including CD8+ T cells and NK cells, thereby inducing an ‘exhausted’ phenotype, concurrent to increasing PD-1 plasma membrane expression." (PMID 33375613, 2020). "AHRR represses AHR and may act as a tumor suppressor; reduced expression was reported in malignant ovarian tissue, and it is hypermethylated in OvCa." (PMID 31923221, 2020). "Interestingly, TCDD and other AHR agonists can both enhance or retard tumor growth in experimental mouse models, depending on context." (PMID 32398692, 2020). "We found that tumours presenting high AhR activity were enriched in luminal tumours." (PMID 32988402, 2020). "We further evaluated the AHR and AR protein level in these tumor tissues using immunoblot assay." (PMID 32404918, 2020). "Kyn, the main product of Trp metabolism pathway catalyzed by TDO2 and indoleamine 2,3-dioxygenase (IDO) in tumor cells, was also demonstrated to activate aryl hydrocarbon receptor (AhR), which may regulate cancer growth and invasion in some malignancies." (PMID 33542896, 2020). "It is worth mentioning that high levels of CYP1B1 may increase the expression of AHR, therefore triggering a feed-forward loop that facilitates tumor progression." (PMID 31370872, 2019). "In various tumor types, AhR has been shown to be involved in tumor formation and progression." (PMID 31212758, 2019). "AHR signaling contributes to the development of a tumor-promoting microenvironment in the surrounding stroma by stimulating signaling pathways and mediators that facilitate angiogenesis and cancer cell motility (including vascular endothelial growth factor and TGFβ)." (PMID 31795255, 2019). "Similarly, in the upper urinary tract, a correlation between AhR expression and tumor grade was demonstrated." (PMID 31212758, 2019). "In addition to this role in detoxification, recent works have also revealed novel roles for AHR in tumor biology." (PMID 31552251, 2019). "Furthermore, in GBM, signaling through HIF1α and AHR can crossregulate each other at several points of contact, coordinating metabolic regulation of anti-tumor immunity as well as tumor growth." (PMID 31866995, 2019).
tumor (continued). "While AhRR effectively blocks AhR signaling, several aspects of the mechanism of AhRR’s functions are poorly understood, including suppression of inflammatory responses and its putative role as a tumor suppressor." (PMID 31035533, 2019). "We then analyzed the correlations between AhR expression and various relevant clinicopathological parameters, including age at time of diagnosis; histologic type; tumor size; grade; local recurrence; distant metastasis; expression of ER, PR, and HER2; and TNBC status." (PMID 30813617, 2019). "On the basis of previous data showing that 3MC induces CYP1B1 expression in tumor cells through AHR, we aimed to evaluate whether GPER may be involved in the expression of CYP1B1 by 3MC." (PMID 31370872, 2019). "Additionally, overexpression and constitutive activation of the AHR have been observed in various types of tumour." (PMID 31554340, 2019). "The dramatic reduction in UVB radiation-induced SCC formation in AHR-null mice may also be due to enhanced anti-tumor immune responses in these animals." (PMID 31795255, 2019). "In the present study, we provide evidence that the effects that hamper the in vivo anti-tumor capability of CAI might occur through the IDO-Kyn-AhR cascade." (PMID 31511064, 2019). "The AHR/ARNT heterodimer regulates genes encoding xenobiotic metabolizing enzymes and mediates the severe toxicity, comprising a wasting syndrome, hepatotoxicity, teratogenesis, and tumour promotion." (PMID 31554340, 2019). "TDO2 also helps tumor immune evasion by activating the AHR through its downstream metabolites." (PMID 31866995, 2019). "Indeed, under some circumstances, kynurenine can be produced in large quantities and can drive AhR-mediated suppression of anti-tumor immune responses." (PMID 30132758, 2018). "Tumor cells and intratumoral stroma were immunostained for AhR." (PMID 29320557, 2018). "Another target of KYNA is the aryl hydrocarbon receptor (AHR), which is considered a xenobiotic receptor, and its activation is associated with the suppression of cellular immune response favoring carcinogenesis and tumor outgrowth." (PMID 29977455, 2018). "AhR protein was observed in both tumor cells and the tumor microenvironment (intratumoral stroma)." (PMID 29320557, 2018). "AhR immunostaining was also observed in both nuclei and cytoplasm of tumor cells." (PMID 29320557, 2018). "Activation via the aryl hydrocarbon receptor (AhR), by affecting cell signaling pathways, might reflect the role of the AhR in tumor progression." (PMID 29707532, 2018). "The role of AHR in cancer is likely to be regulated by additional factors such as its binding to specific ligands and the landscape of oncogenes/tumor suppressors of each tumor." (PMID 30254109, 2018). "The sub-localization of AhR (nuclear or cytoplasmic) was analyzed in tumor cells from all samples." (PMID 29320557, 2018). "Furthermore, a wide variety of tumor types exhibit enhanced AHR expression with constitutive occurrence in the nucleus, suggesting a persistently activated AHR in tumors." (PMID 30501068, 2018). "IL-22 expression and RORγt/AhR mRNA in BALF was also remarkably increased in tumor site." (PMID 30473538, 2018). "The presence of AhR in tumor-infiltrating lymphocytes was confirmed by the use of CD4 antibodies." (PMID 29320557, 2018). "However, increased IL-22 concentration and RORγt/AhR mRNA relative level was only found in lung-resident tumor site in lung adenocarconoma patients." (PMID 30473538, 2018). "We studied AhR expression with immunostainning assay in the patient tumour lesions." (PMID 28782227, 2018). "Ectopic AHR expression increases tumor cell motility and invasion." (PMID 29735912, 2018). "Several key pathway molecules in the tryptophan pathway, including IDO-1, TDO-2, and kynurenine, participate in controlling immune tolerance and promoting tumor escape by regulating T cells and the proliferation, differentiation, and apoptosis of tumor cells via the AhR." (PMID 29487603, 2018).
tumor (continued). "In addition, Liu and colleagues identified a Kyn–AhR pathway-dependent mechanism that promoted tumor-repopulating cell immune escape by increasing PD-1 binding to CD8+ T cells." (PMID 30068361, 2018). "In HCC development, AHR plays a critical role in tumor cell immunosuppression." (PMID 29301348, 2018). "Altogether, those studies show the AhR controls cell proliferation of progenitor cells, but also tumor cells and might represent a future therapeutic target for a large pathological spectrum from neurodegenerative diseases to brain cancers." (PMID 30149528, 2018). "Interestingly, whereas AHR inhibitors significantly slowed tumor cell migration, both 5 μM DIM and 1 nM TCDD accelerated cell migration (reduced exposed area) of Hs578T or SUM149 cells in the scratch wound assay." (PMID 29735912, 2018). "Several studies have demonstrated that the AhR may be a tumor suppressor under certain circumstances." (PMID 29487603, 2018). "Both of these AHR agonists were previously reported to decrease human tumor cell growth." (PMID 29735912, 2018). "And AhR is higher expressed in short AR‐Q tumour compared to that in long AR‐Q patient." (PMID 28782227, 2018). "The research mentioned earlier suggests that AhR activation may contribute to inflammatory signaling within a tumor microenvironment through multiple MoAs." (PMID 29487603, 2018). "However, other studies have suggested that, under some circumstances, the AHR can oppose tumor aggression." (PMID 29735912, 2018). "Additionally, systemically circulating endogenous ligands, including indoxyl sulfate and indirubin, as well as exposure to potent environmental ligands in combination with increased AHR expression in tumor cells, result in constant activation of AHR." (PMID 30501068, 2018). "The AhR has been reported to take part in the modulation of innate immunity and adaptive immunity, which may be involved in tumorigenesis and tumor immune surveillance." (PMID 29487603, 2018). "AHR was mainly expressed in tumor islands and stromal inflammatory cells." (PMID 30144817, 2018). "Although several studies have suggested that AhR may be a suppressor of tumor under specified conditions, the effects of AhR activation have also been suggested to occupy a significant place in immune modulation and carcinogenesis in vivo and in vitro." (PMID 30090104, 2018). "The data mentioned earlier suggest that the AhR could be an intriguing regulator and potential therapeutic target for angiogenesis and metastasis during tumor development." (PMID 29487603, 2018). "AHR, a unique chemical sensor activated by a large number of xenobiotics, has been considered a major regulator of xenobiotic-induced carcinogenesis, but its role in the processes of tumor initiation and development remains to be elucidated." (PMID 27283490, 2017). "A similar network could also limit liver carcinogenesis in presence of AhR by restricting tumor growth and malignant progression." (PMID 28874739, 2017). "Although both tumour-suppressor and pro-oncogenic functions have been reported for AhR in different cancers, the relationship between AhR and cancer metastasis remains unclear." (PMID 28195146, 2017). "It seems that AHR activation in AML cells plays an inhibition effect on AML tumor growth; this is consistent with the recent finding that AHR may promote HIF1α degradation in lymphocyte metabolism and indirectly suppress the HIF1α pathway." (PMID 29212263, 2017). "In an effort to develop an efficient strategy for AML treatment, we found that BA could slightly suppress tumor growth through ROS generation and AHR activation with subsequent HIF1α suppression in THP1 cells." (PMID 29212263, 2017). "The role of AHR in tumor pathology is complicated and not fully understood yet." (PMID 27752740, 2017). "Some studies have suggested both tumour suppressive and oncogenic functions for ligand-activated AhR10; however, the other physiological functions of AhR remain unknown." (PMID 28195146, 2017).